CERS5 (ceramide synthase 5)
Description:
Ceramide synthase that catalyzes the transfer of the fatty acyl chain from fatty acyl-CoA to a sphingoid base, with high selectivity toward palmitoyl-CoA (hexadecanoyl-CoA; C16:0-CoA). Can use different sphingoid bases as substrates for ceramide synthesis, such as sphinganine in de novo synthesis, and sphing-4E-enine (sphingosine), (4R)-hydroxysphinganine (phytosphingosine) or sphinga-4E,14Z-dienine in salvage pathways. Other fatty acyl-CoAs such as long-chain saturated stearoyl-CoA (octadecanoyl-CoA; C18:0-CoA), myristoyl-CoA (tetradecanoyl-CoA; C14:0-CoA), and monounsaturated oleoyl-CoA (9Z-octadecenoyl-CoA; C18:1-CoA) can also act as acyl donors, but with less efficiency than hexadecanoyl-CoA (By similarity). Plays a role in de novo ceramide synthesis and surfactant homeostasis in pulmonary epithelia (By similarity).
Synonyms: LASS5; Trh4; MGC45411; FLJ25304
Tractability: Antibody: UniProt predicts a signal peptide or a membrane-spanning region. PROTAC: ubiquitination databases record sites on it.
Target class: Enzyme; Transferase
Gene: Protein-coding gene on chromosome 12 (50,129,289 to 50,167,533, reverse strand). Ensembl gene ENSG00000139624.
Subcellular location: Endoplasmic reticulum membrane
Subcellular location (Human Protein Atlas): Nuclear membrane; Endoplasmic reticulum; Primary cilium
Pathways (Reactome):
Metabolism: Sphingolipid de novo biosynthesis
Gene Ontology:
Molecular function: protein binding; sphingosine N-acyltransferase activity; DNA binding
Biological process: ceramide biosynthetic process; sphingomyelin biosynthetic process; sphingolipid biosynthetic process; sphingolipid metabolic process
Cellular component: cytoplasmic side of endoplasmic reticulum membrane; endoplasmic reticulum membrane; endoplasmic reticulum; membrane
Genetic constraint (gnomAD): Loss-of-function variants: 27 observed, 37.95 expected, observed/expected ratio (o/e) 0.71, 90% interval 0.52 to 0.98. The upper end of that interval is the gene's LOEUF score, 0.98, which puts it in group 4 of 6, group 1 being the genes least tolerant of losing a copy. Missense variants: 298 observed, 372.2 expected, observed/expected ratio (o/e) 0.8, 90% interval 0.73 to 0.88. Synonymous variants: 120 observed, 138.81 expected, observed/expected ratio (o/e) 0.86, 90% interval 0.75 to 1.01.
Homologues: Orthologues: chimpanzee CERS5 (99% identical), pig CERS5 (91% identical), dog CERS5 (90% identical), rat Cers5 (79% identical), mouse Cers5 (77% identical), rabbit CERS5 (74% identical), tropical clawed frog cers5 (73% identical), zebrafish cers5 (69% identical), guinea pig CERS5 (58% identical), Drosophila melanogaster schlank (41% identical), Caenorhabditis elegans hyl-1 (28% identical), Caenorhabditis elegans hyl-2 (27% identical). Paralogues in human: CERS6 (63% identical), CERS4 (42% identical), CERS2 (41% identical), CERS3 (39% identical), CERS1 (25% identical).
Diseases named in the same sentence as CERS5 in open-access papers:
CERS5 is named in the same sentence as 40 diseases in open-access papers, as found by Europe PMC text mining. Sharing a sentence is not in itself a finding about the gene and the disease. The quoted sentences say what the papers report.
Insulin resistance (10 papers, 2018 to 2024). Increased resistance towards insulin, that is, diminished effectiveness of insulin in reducing blood glucose levels. "Remarkably, mice deficient in ceramide synthase 5 (CerS5), which exhibit lower hepatic levels of Cer 16:0, were protected from developing obesity and insulin resistance when fed a high-fat diet." (PMID 33113993, 2020). "Insulin resistance caused by a HFD is alleviated by CerS5 or CerS6 gene deletion, which prevents C16 ceramide synthesis in liver and adipose tissue." (PMID 30131496, 2018). "To achieve this goal, we investigated the effect of local in vivo shRNA-mediated gene silencing of CerS1 and CerS5 on the bioactive lipid accumulation and insulin signaling pathway in gastrocnemius muscle of mice with diet-induced insulin resistance." (PMID 35053322, 2022). "CerS5 deficiency prevented WAT C16-ceramide increase and improved glucose intolerance, insulin resistance, WAT mass, adipocyte size, and triglycerides levels in mice challenged with HFD." (PMID 32849282, 2020). "Therefore, inhibition of CerS6, and perhaps CerS1 and CerS5, may serve as an attractive therapeutic approach for treating insulin resistance, obesity, fatty liver, and NASH." (PMID 32849276, 2020). "Hammerschmidt and coworkers showed that CerS6‐derived C16 ceramide but not CerS5‐derived C16 ceramide protects from high‐fat diet‐induced obesity and insulin resistance." (PMID 31692231, 2020). "In particular, hepatic Cer 16:0, specifically formed by CerS6, but not by CerS5, binds to mitochondrial fission factor (MFF), which, activated, promotes mitochondrial fission, causing mitochondrial dysfunction, an event that has been related to insulin resistance and obesity." (PMID 37108620, 2023). "Altogether, this study highlighted new insight about the implication of CerS5 in maintaining whole-body homeostasis, but independently from its expression in muscle, suggesting that C16-ceramide produced by CerS5 may not play a role in the onset of muscle insulin resistance." (PMID 32849282, 2020).
colon carcinoma (8 papers, 2019 to 2024). "In our study, we observed that CerS5-ko mice were also more susceptible to DSS-induced colitis as well as to AOM/DSS-induced colitis-associated colon cancer." (PMID 32630271, 2020). "In summary, we show that CerS5-ko mice were more susceptible to dextran sodium sulfate-induced colitis and azoxymethane/dextran sodium sulfate-induced colitis-associated colon cancer." (PMID 32630271, 2020). "In human colon cancer tissue, CerS6 expression rather increases, whereas CerS5 expression decreases especially in late-stage colon cancer." (PMID 38635059, 2024). "In aggressive growing colon cancer cells, CerS5 depletion leads to an upregulation of growth factor–related proteins like K-Ras and oncogenes like hepatoma-derived growth factor–related protein 2 (HDGFL2)." (PMID 38635059, 2024). "In line with this, it has been shown that patients with low CerS5 expression in late-stage colon tumours have a poor prognosis." (PMID 38635059, 2024). "Instead, CerS5-ko mice were more susceptible to DSS-induced colitis and AOM/DSS-induced colon cancer which was related to disturbed T cell functions." (PMID 38635059, 2024). "Accumulating evidence suggests that the overexpression of Cers2 leads to increased cell proliferation in colon cancer cell lines, while high Cers5 expression has been found in colorectal cancer tissue and is associated with poorer patient outcomes." (PMID 37298127, 2023). "Conversely, CerS5 knockout was shown to stimulate colon cancer development in azoxymethane (AOM) and dextran sulfate sodium (DSS) colitis-associated colon cancer models." (PMID 35565311, 2022). "In addition, high expression of CerS5 has been reported to predict a poor prognosis in gastric and colon cancer." (PMID 39397024, 2024). "A decrease in CerS5 expression was only observed in metastatic colon tumours." (PMID 38635059, 2024). "Next, we found that depletion of Cers5 could significantly repress the colon tumor as shown by tumor numbers, tumor volumes, and tumor diameters in miR-148a–/– mice." (PMID 34914638, 2022). "In addition to the acute DSS mouse model, we investigated colon tumor development in CerS5-wt and CerS5-ko mice, as well as in mice with CerS5 ablation restricted to colon epithelial cells (CerS5fl/fl/VilCre) using the AOM/DSS mouse model." (PMID 32630271, 2020). "Importantly, high CERS5 expression has also been found to be associated with reduced colon cancer patient survival; this could be mediated by a transition from apoptotic to autophagic signaling, and contribution of CERS5 to colon cancer progression." (PMID 31801289, 2019). "CerS5 Vil1-Cre mice, where CerS5 is only depleted in colon epithelial cell, do not differ in their susceptibility against AOM/DSS-induced colon cancer in comparison to wt mice." (PMID 38635059, 2024). "Depletion of CerS5 in aggressive growing colon cancer cells has pro-tumourigenic effects, whereas in non-aggressive growing colon cancer cells, it has rather anti-tumourigenic effects in vitro and in vivo." (PMID 38635059, 2024).
Obesity (8 papers, 2020 to 2023). Accumulation of substantial excess body fat. "CerS5 deficiency was reported to ameliorate high‐fat diet‐induced obesity." (PMID 31692231, 2020). "However, when challenged with high fat diet CerS5 knockout animals protected against diet induced obesity and associated with reduced levels of leptin relative to wild type animals." (PMID 32849276, 2020). "Previous publications implicated CerS5 and CerS6 in obesity and glucose intolerance." (PMID 31692231, 2020). "Ceramide synthase 5 (CERS5) was previously found to be responsible for ceramide synthesis, as well as to contribute to diet-induced obesity and hepatic triglyceride accumulation in mice." (PMID 34914638, 2022). "Previously, a whole‐body knockout of CerS5 was reported to ameliorate high‐fat diet‐induced obesity." (PMID 31692231, 2020). "Additionally, on diet induced obesity CerS5 knockout animals displayed improved glucose tolerance, insulin sensitivity, and reduced white adipose inflammation compared to wild type animals." (PMID 32849276, 2020). "Furthermore, we have reported previously that body-wide ablation of CerS6- but not CerS5-dependent ceramide synthesis protects mice from diet-induced obesity and insulin resistance." (PMID 38016943, 2023). "However, our in vitro studies showed that palmitate excess does not affect CerS5 expression in N43/5 cells, implying that hypothalamic CerS5 in vivo is modulated by other obesity-related factors independent of palmitate." (PMID 38016943, 2023).
colorectal cancer (6 papers, 2021 to 2023). A primary or metastatic malignant neoplasm that affects the colon or rectum. "CerS5 has been noted to be upregulated in colorectal cancer and was associated with poor patient survival and 5-year cancer recurrence." (PMID 34069611, 2021). "For example, we observed the enhanced DEGS2's consumption amount of dhCer as reported in colorectal cancer, the significantly inhibited salvage pathway by overexpressed CERS5, and the activated sphingosine generation pathway by overexpressed ASAH1." (PMID 37999228, 2023). "In addition, CerS5 mRNA expression is elevated in patient-derived colorectal cancer (CRC) tissue in comparison to normal colonic mucosa, and CerS5 can be used as a marker for CRC." (PMID 37760612, 2023). "CerS5 has also been noted to be a biomarker for colorectal cancer." (PMID 34069611, 2021).
colitis (4 papers, 2020 to 2025). Inflammation of the colon. "Our data show that CerS5-ko mice were more susceptible to DSS-induced colitis and AOM/DSS-induced CAC." (PMID 32630271, 2020). "Interestingly, CerS5 and CerS6 knockdown was shown to sensitize mice to azoxymethane/dextran sodium sulfate-induced colitis and increased cases of colitis-associated colon cancer." (PMID 34069611, 2021). "For example, CerS5 and CerS6 knockout mice show increased susceptibility to DSS-induced colitis and colitis-associated colon cancer." (PMID 40597360, 2025). "Similar to global knockout of CerS5, total body loss of CerS6 exacerbated colitis pathology scores and increased neutrophil infiltration in mice with DSS-induced colitis." (PMID 38398179, 2024). "Despite the implications of CerS5 in CRC, global knockout of CerS5 exacerbated pathology scores and inflammation in mice with DSS-induced colitis, and increased tumor burden in AOM/DSS mice." (PMID 38398179, 2024). "Therefore, our data indicate that depletion of CerS5 in colon epithelial cells is not responsible for the higher sensitivity of CerS5–ko mice against DSS-induced colitis and CAC." (PMID 32630271, 2020).
cardiac hypertrophy (3 papers, 2024 to 2025). "The key finding in this study is that CERS2 KD leads to pathway changes that support a more severe HF progression, while CERS5/6 KD leads to less aggressive changes in pathways crucial to cardiac hypertrophy progression." (PMID 41003018, 2025). "Ceramide synthase 5 (CerS5), which mediates the synthesis of Cer (16:0) and Cer (14:0), promotes autophagy and cardiac hypertrophy because of lipotoxicity." (PMID 38438248, 2024). "We hypothesize that the lipid products generated by CerS2—VLC ceramides—are protective during cardiac hypertrophy, while the products of CerS5/6—LC ceramides—promote the progression and development of hypertrophy." (PMID 41003018, 2025).
breast adenocarcinoma (2 papers, 2022 to 2023). "A study by Obeid's group showed in human breast adenocarcinoma cells that CerS5/6 played an important role in ceramide synthesis (mainly C14/16-cer) using the sphingosine salvage pathway." (PMID 37178918, 2023). "By contrast, the effects of fumonisins on sphingolipids in this study on turkeys, including the effects on dihydroceramides, glycosylceramides, and sphingomyelins, resemble the changes to sphingolipids observed in CerS5 knockout MCF-7 human breast adenocarcinoma cells." (PMID 35269655, 2022).
breast carcinoma (2 papers, 2016 to 2023). "Moreover, breast cancer patients with higher mRNA expression of CerS4, along with CerS1 and CerS5, show a worse prognosis than those with low CerS expression levels." (PMID 37760612, 2023).
aortic valve stenosis (1 paper, 2025). Aortic valve stenosis (AVS) is a condition characterized by narrowing of the heart's aortic valve opening. "Recently, a study reported that ceramide synthase 5 (CerS5), a critical enzyme for C16 ceramide synthesis plays a crucial role in the valvular interstitial cells (VIC) and high‐fat/high‐cholesterol diet (HFHCD) fed mice during the development of aortic valve stenosis and inflammation." (PMID 41335598, 2025).
cardiomyopathy (1 paper, 2025). A disease of the heart muscle or myocardium proper. "Following CERS2 KD and extensive washing to remove dead cells, increases in ECM organization and cardiomyopathy pathways were observed as well as decreases in pathways involved in the cell cycle, while we observed opposing changes following CERS5/6 KD despite the cell death observed with CERS2 KD." (PMID 41002968, 2025). "Notably, we also observed decreases in cardiovascular disease pathways, like cardiomyopathy, following CERS5/6 KD." (PMID 41002968, 2025).
chronic heart failure (1 paper, 2020). "In humans, CerS1 and CerS5 mRNA expression declined not only age dependently but was also associated with chronic heart failure, suggesting that age‐ and critical illness‐related changes of specific Cer species contribute to myo‐pathological disorders." (PMID 31692231, 2020). "In comparison with a coeval healthy control cohort, a reduced CerS1 and CerS5 mRNA expression was found in muscle biopsies from aged patients suffering from chronic heart failure." (PMID 31692231, 2020). "Patients with chronic heart failure suffering from muscle weakness presented with decreased CerS1 and CerS5 expression, suggesting that CerS1 and CerS5 may also be linked to functional deficiencies of skeletal muscle in humans." (PMID 31692231, 2020). "Notably, reduced CerS1 and CerS5 mRNA expression was observed in chronically ill patients suffering from chronic heart failure, suggesting that decline of CerS1 and CerS5 gene expression is functionally relevant for the development of critical illness‐associated myopathies." (PMID 31692231, 2020). "Moreover, CerS1 and CerS5 mRNA expression was also reduced in muscle biopsies from patients in advanced stage of chronic heart failure (CHF) suffering from muscle wasting and frailty." (PMID 31692231, 2020).
COVID-19 (1 paper, 2023). A disease caused by infection with severe acute respiratory syndrome coronavirus 2. "However, no significant regulation was observed in the gene expression of CERS1, CERS3, CERS5, and CERS6 within the same COVID-19 group." (PMID 37566018, 2023).
dermatitis (1 paper, 2019). An inflammatory process affecting the skin. "In FAg-induced dermatitis, the expression of CerS1, CerS4, and CerS5 decreased, whereas the expression of CerS2 and CerS3 mildly increased with statistical significance." (PMID 30838224, 2019). "In IMQ-induced dermatitis, the expression of CerS1, CerS4, and CerS5 had a tendency to decrease, whereas the expression of CerS3 increased by 4.6-fold." (PMID 30838224, 2019).
diabetic cardiomyopathy (1 paper, 2015). Diabetic cardiomyopathy is a disorder of the heart muscle in people with diabetes. "In addition, ceramides generated by CerS5 were responsible for lipotoxic cardiomyopathy and hypertrophy in mouse models of diabetic cardiomyopathy." (PMID 26288989, 2015).
glioma (1 paper, 2024). A benign or malignant brain and spinal cord tumor that arises from glial cells (astrocytes, oligodendrocytes, ependymal cells). "We further show that this AS signature can be regulated by mutant EGFR or IDH1 and elucidate the functional mechanisms of AS events in genes CERS5 and MPZL1 in promoting glioma malignancy." (PMID 38662454, 2024). "AS of CERS5 and MPZL1 influences the oncogenic potential of glioma cells." (PMID 38662454, 2024).
hepatocellular carcinoma (1 paper, 2025). A malignant tumor that arises from hepatocytes. "Further, elevated LPL and CERS5/6 expression are significantly associated with reduced survival in hepatocellular carcinoma." (PMID 41256541, 2025). "Notably, CERS5 and CERS6 emerge as actionable enectors of IL-6 associated hepatic dysfunction: higher CERS5/6 expression correlates with reduced survival in hepatocellular carcinoma." (PMID 41256541, 2025).
Hypertension (1 paper, 2023). The presence of chronic increased pressure in the systemic arterial system. "Notably, genome-wide association studies (GWAS) have established a connection between CerS5 and hypertension, shedding light on its potential significance in cardiovascular health and suggesting that CerS5′s impact on ceramide species may have implications for hypertension." (PMID 38137595, 2023).
liver fibrosis (1 paper, 2025). "CerS5 knockout not only reduces the expression of the key enzyme Cyp27a1 but also elevates the levels of 12a-OH BAs, specifically CAs and DCAs, which play a role in HSC activation and the advancement of liver fibrosis." (PMID 40557038, 2025).
prostate carcinoma (1 paper, 2021). A carcinoma that arises from epithelial cells of the prostate gland. "Overexpression of ceramide synthase 5 that specifically produces C16 ceramide enables erianin to induce apoptosis in castration-resistant prostate cancer cells." (PMID 34604081, 2021).